TEX10 (testis expressed 10)
Description:
Functions as a component of the Five Friends of Methylated CHTOP (5FMC) complex; the 5FMC complex is recruited to ZNF148 by methylated CHTOP, leading to desumoylation of ZNF148 and subsequent transactivation of ZNF148 target genes. Component of the PELP1 complex involved in the nucleolar steps of 28S rRNA maturation and the subsequent nucleoplasmic transit of the pre-60S ribosomal subunit.
Synonyms: FLJ20287; bA208F1.2; Ipi1
Tractability: Small molecule: a structure with a bound ligand is known. PROTAC: ubiquitination databases record sites on it; its protein half-life has been measured.
Gene: Protein-coding gene on chromosome 9 (100,302,072 to 100,352,957, reverse strand). Ensembl gene ENSG00000136891.
Subcellular location: Nucleus, nucleoplasm; Cytoplasm; Nucleus, nucleolus
Subcellular location (Human Protein Atlas): Nucleoplasm; Mitochondria
Pathways (Reactome):
Metabolism of RNA: Major pathway of rRNA processing in the nucleolus and cytosol
Gene Ontology:
Molecular function: protein binding
Biological process: cleavage in ITS2 between 5.8S rRNA and LSU-rRNA of tricistronic rRNA transcript (SSU-rRNA, 5.8S rRNA, LSU-rRNA)
Cellular component: MLL1 complex; nucleus; rixosome complex; cytoplasm; nucleoplasm; nucleolus
Genetic constraint (gnomAD): Loss-of-function variants: 22 observed, 89.68 expected, observed/expected ratio (o/e) 0.25, 90% interval 0.17 to 0.35. The upper end of that interval is the gene's LOEUF score, 0.35, which puts it in group 1 of 6, group 1 being the genes least tolerant of losing a copy. Missense variants: 851 observed, 1,041.7 expected, observed/expected ratio (o/e) 0.82, 90% interval 0.77 to 0.87. Synonymous variants: 364 observed, 378.34 expected, observed/expected ratio (o/e) 0.96, 90% interval 0.88 to 1.05.
Homologues: Orthologues: chimpanzee TEX10 (99% identical), macaque TEX10 (99% identical), dog TEX10 (96% identical), pig TEX10 (94% identical), rabbit TEX10 (94% identical), guinea pig TEX10 (93% identical), mouse Tex10 (89% identical), rat Tex10 (89% identical), tropical clawed frog tex10 (56% identical), zebrafish tex10 (47% identical), Drosophila melanogaster CG1575 (19% identical), Caenorhabditis elegans Y48A6C.4 (11% identical). Paralogues in human: RMDN3 (10% identical), RMDN2 (8% identical), RMDN1 (6% identical).
Diseases named in the same sentence as TEX10 in open-access papers:
TEX10 is named in the same sentence as 18 diseases in open-access papers, as found by Europe PMC text mining. Sharing a sentence is not in itself a finding about the gene and the disease. The quoted sentences say what the papers report.
melanoma (4 papers, 2020 to 2025). A malignant, usually aggressive tumor composed of atypical, neoplastic melanocytes. "NOLC1, PAICS, and TEX10 expression are associated with cancer stemness, poor prognosis, and resistance to interventional chemo/radiotherapy in patients with breast cancer, esophageal cancer, hepatocellular carcinoma or melanoma." (PMID 37435077, 2023).
hepatocellular carcinoma (3 papers, 2019 to 2024). A malignant tumor that arises from hepatocytes. "For example, TEX10 was upregulated and promoted cancer stem cell properties and chemoresistance in hepatocellular carcinoma." (PMID 31481019, 2019).
urinary bladder carcinoma (3 papers, 2021 to 2024). "Herein, we deeply investigated the underlying mechanism of TEX10 in urinary bladder carcinoma for providing valuable supports to the researches on the urinary bladder carcinoma." (PMID 34966825, 2021). "Thus, studying the association of TEX10 and Wnt/β-catenin channel is beneficial to comprehend the underlying mechanism of TEX10 in urinary bladder carcinoma." (PMID 34966825, 2021). "Accordingly, targeting TEX10 is likely to offer a novel and feasible therapeutically related strategy for inhibiting urinary bladder carcinoma tumorigenicity." (PMID 34966825, 2021). "The mRNA state of TEX10 was also upregulated in the urinary bladder carcinoma tissue as compared with that within the general counterpart." (PMID 34966825, 2021). "For this reason, the mentioned results suggested that TEX10 facilitates the proliferating process of urinary bladder carcinoma cell in vitro." (PMID 34966825, 2021). "Nevertheless, rare study investigated the correlations of TEX10 and Wnt/β-catenin channel within urinary bladder carcinoma." (PMID 34966825, 2021). "We investigated the role of TEX10 in the migrating and invading processes of urinary bladder carcinoma cells by Boyden's chamber tests and Matrigel-coated tests, respectively." (PMID 34966825, 2021). "First of all, we found that TEX10 protein level rose noticeably within the human urinary bladder carcinoma tissue in contrast with the normal tissue in two sets." (PMID 34966825, 2021). "After TEX10 knockdown in the bladder carcinoma cell lines, the expression of TEX10 was dramatically reduced, and the growth of the mentioned cells was suppressed." (PMID 34966825, 2021). "All the mentioned results suggested that the low level of TEX10 inhibited the migrating and invading behaviors of urinary bladder carcinoma cell." (PMID 34966825, 2021). "For investigating the influence exerted by TEX10 on the growth of urinary bladder carcinoma cells, this study sets two TEX10 shRNAs to reduce TEX10 in T24 cell." (PMID 34966825, 2021). "Although TEX10 positively regulated the XRCC6 level and signaling of Wnt/β-catenin in urinary bladder carcinoma according to this work, the underlying molecular mechanisms involving TEX10, XRCC6, and Wnt/β-catenin channel remain to be further identified." (PMID 34966825, 2021). "On the contrary, the overexpression of TEX10 promoted the proliferation of urinary bladder carcinoma cell." (PMID 34966825, 2021). "And TEX10 presented great possibility to be one new and vital therapeutically related target for urinary bladder carcinoma treatment." (PMID 34966825, 2021). "Reduced TEX10 level inhibited urinary bladder carcinoma cell proliferating process and metastasis in vitro and xenograft tumorigenicity in vivo." (PMID 34966825, 2021). "For more effectively studying the correlation of TEX10 and urinary bladder carcinoma growth, we used stable TEX10-overexpressing or control T24 cells into flank area of female BALB/c nude rats." (PMID 34966825, 2021). "The present work is aimed at revealing TEX10 expression and biological function within urinary bladder carcinoma and elucidating the potential mechanisms." (PMID 34966825, 2021). "Results showed that TEX10 is abundant in urinary bladder carcinoma, and its protein level was related to poor disease-free survival in a positive manner." (PMID 34966825, 2021). "By performing Matrigel-coated and Boyden's chamber tests, we discovered that the low level of TEX10 inhibited the migrating and invading processes of urinary bladder carcinoma cell." (PMID 34966825, 2021). "In conclusion, our study manifested that TEX10 serves as a critical role in bladder carcinoma tumorigenesis." (PMID 34966825, 2021).
urinary bladder carcinoma (continued). "Another study also demonstrated that TEX10 (testis expressed 10) promoted radioresistance in urinary bladder carcinoma by stabilising XRCC6 (x-ray repair cross complementing 6), a key factor required for efficient NHEJ upon induction of DNA damage by agents such as ionising radiation." (PMID 36980267, 2023). "Interestingly, we discovered the noticeable relation of TEX10 and XRCC6 in urinary bladder carcinoma that TEX10 promotes the level of XRCC6." (PMID 34966825, 2021). "Therefore, the mentioned result implied that TEX10 level was positively related to the urinary bladder carcinoma growth in vivo." (PMID 34966825, 2021). "Furthermore, the overexpression of TEX10 was observed to notably contribute to the tumor growth in the rats with urinary bladder carcinoma." (PMID 34966825, 2021). "However, protein level high in cancerous tissue, suggesting that protein level of TEX10 was upregulated in urinary bladder carcinoma." (PMID 34966825, 2021). "It indicates that TEX101 and TEX10 play different roles in bladder carcinoma." (PMID 34966825, 2021). "However, few studies on the functions of TEX10 have been reported in carcinomas, especially in bladder carcinoma." (PMID 34966825, 2021). "Moreover, we found that the TEX10 knockdown remarkably improved the sensitivity of urinary bladder carcinoma cells to IR." (PMID 34966825, 2021). "In brief, this work revealed that TEX10 could exert a significant carcinogenic effect on urinary bladder carcinoma tumorigenesis and radiotherapy resistance through the activation of XRCC6-related channels." (PMID 34966825, 2021). "Moreover, the low TEX10 expressing state presented an improved DFS in urinary bladder carcinoma patients." (PMID 34966825, 2021). "Therefore, TEX10 might be a promising radiosensitization drug target for urinary bladder carcinoma treatment via mediating NHEJ impairment via XRCC6." (PMID 34966825, 2021). "Moreover, TEX10 gene knockout reduced the radiotherapy resistance of urinary bladder carcinoma." (PMID 34966825, 2021). "Thus, this work investigated the expression and biological function of Tex10 in bladder carcinoma." (PMID 34966825, 2021). "Moreover, according to the observation, active β-catenin protein content markedly declined in TEX10-silenced cell, while the overall β-catenin protein level kept stable in the mentioned cell, suggesting that the TEX10 knockdown downregulates β-catenin activation in urinary bladder carcinoma." (PMID 34966825, 2021). "Furthermore, this study confirmed that TEX10 silencing inhibited the β-catenin and level activation of cyclin D1 and c-Myc, demonstrating that TEX10 might promote the tumorigenesis of urinary bladder carcinoma via increasing XRCC6 level to enhance the signaling of Wnt/β-catenin." (PMID 34966825, 2021). "Nevertheless, TEX10 expressions and functions within bladder carcinoma are still not known." (PMID 34966825, 2021).
liver cancer (2 papers, 2022 to 2026). An epithelial or non-epithelial malignant neoplasm that arises from the liver. "Thus, the underlying mechanism of Tex10 in liver cancer is needed to be clarified." (PMID 35156514, 2022). "The RSU1P2/let-7a/Tex10 axis is involved in the development of liver cancer and can be an interesting target due to its regulatory function in the expression of CSC-related genes, as well as in processes like apoptosis and epithelial-to-mesenchymal transition." (PMID 41431719, 2026). "In this study, inverse correlation between let-7a and Tex10 level was identified in liver cancer tissues." (PMID 35156514, 2022). "According to the findings of previous report, highly expressed Tex10 in liver cancer cells and liver cancer stem cells can promote cancer stem cell properties." (PMID 35156514, 2022). "In this study, Tex10 mRNA level was significantly raised in liver cancer cell lines HepG2, HCCLM3, Huh7, and Hep3B than that in normal liver cell-line THLE-2 (p < 0.05)." (PMID 35156514, 2022). "Previous report has found that Tex10 is raised in liver cancer tissues and cells, and Tex10 dysregulation is closely related with cancer stem cell properties." (PMID 35156514, 2022). "RSU1P2 positively regulates Tex10 mRNA expression by targeting let-7a in liver cancer." (PMID 41431719, 2026). "Importantly, Tex10 has been found to be elevated in liver cancer cells and liver cancer stem cells, as well as Tex10 overexpression facilitates cancer stem cell properties by activating STAT3 pathway." (PMID 35156514, 2022). "We verified that LncRNA RSU1P2/let-7a/Tex10 pathway promoted liver cancer cell proliferation, invasion, EMT and the expression of cancer stem cell-related genes in vitro and confirmed our hypothesis in vivo." (PMID 35156514, 2022). "Therefore, LncRNA RSU1P2 promotes tumorigenesis and cancer stem cell-like properties in liver cancer through let-7a/Tex10 pathway." (PMID 35156514, 2022). "Therefore, we assumed that LncRNA RSU1P2 acted as an oncogene in liver cancer by promoting Tex10 via sponging let-7a." (PMID 35156514, 2022). "Thus, we have revealed the role of LncRNA RSU1P2/let-7a/Tex10 pathway in controlling tumorigenesis and cancer stem cell-like properties in liver cancer, which may supply potential therapeutic targets for liver cancer treatment." (PMID 35156514, 2022). "In this study, Tex10 restoration abolished the inhibition effect of RSU1P2+ let-7a on cell viability, proliferation, invasion, EMT of liver cancer cells, and the expressions of cancer stem cell-related genes." (PMID 35156514, 2022). "Besides, LncRNA RSU1P2 facilitates liver cancer cells proliferation, invasion, EMT, and cancer stem cell-like properties through let-7a/Tex10 pathway in vitro." (PMID 35156514, 2022). "Therefore, our findings suggested that Tex10 was involved in LncRNA RSU1P2/let-7a mediated promotion of the tumorigenesis and cancer stem cell-like properties in liver cancer." (PMID 35156514, 2022). "Moreover, there was a positive correlation between RSU1P2 and Tex10 in liver cancer tissues, and RSU1P2 positively regulated Tex10 mRNA and protein expressions in HCCLM3 and HepG2 cells." (PMID 35156514, 2022).
colorectal cancer (1 paper, 2020). A primary or metastatic malignant neoplasm that affects the colon or rectum. "This study performs genome‐wide RNA interference (RNAi) screening to identify testis expressed 10 (TEX10) as an essential gene in colorectal cancer (CRC)." (PMID 32995120, 2020).
cancer (7 papers, 2019 to 2024). A tumor composed of atypical neoplastic, often pleomorphic cells that invade other tissues. "The RNAseq results suggested that TEX10 is associated with several cancer‐related signal pathways, such as TNF signaling, EMT, and hypoxia." (PMID 32995120, 2020). "Although several studies have linked TEX10 to different types of cancer, its role in gastrointestinal tumors remains unknown." (PMID 32995120, 2020). "Previous studies have reported that TEX10 participates in several regulation processes, including controlling ribosome biogenesis, which is strongly linked with carcinoma development, and regulating cell cycle, critically impacting malignant progression of carcinomas." (PMID 34966825, 2021). "Tex10 mRNA level was significantly elevated in cancer tissues (0.25 ± 0.09 vs 0.85 ± 0.21, p < 0.05)." (PMID 35156514, 2022). "TEX101, belonging to the same family with TEX10, was also documented in several tissues' carcinoma cell in HNSCC patients, while the general squamous epithelium had the immunonegative characteristic." (PMID 34966825, 2021). "With the mentioned observations in mind, we proposed that the dysregulated expression of TEX10 was also closely related to the pathogenesis and development of carcinomas." (PMID 34966825, 2021). "In conclusion, our study identified TEX10 as an essential gene in CRC that affects the proliferation of cancer cells and the prognosis of patients." (PMID 32995120, 2020). "Interestingly, other components of the Rix1 complex (WDR18 and TEX10) are also found overexpressed in cancer, indicating that the function of this complex is required to support high rates of ribosome biogenesis in cancer." (PMID 38633862, 2024). "Notably, TEX10 might regulate carcinoma cell proliferating process and metastasis via XRCC6, thereby controlling the signaling of Wnt/β-catenin and DNA repair channel." (PMID 34966825, 2021).
tumor (4 papers, 2020 to 2025). "After 6 weeks of injection, we harvested the tumor and reported that tumor sizes were noticeably larger within the TEX10-overexpressing rats than those in the controls." (PMID 34966825, 2021). "Tumor weights from the TEX10-overexpressing group were obviously increased, and the tumors in TEX10-overexpressing group displayed a higher growth rate." (PMID 34966825, 2021). "We measured the growth of subcutaneous tumors and found that tumor growth was significantly slower in the TEX10 knockdown group than that in the control group." (PMID 32995120, 2020). "However, the lncRNA GATA3-AS1 sponges miR-30b-5p, which in turn leads to the upregulation of the target gene Tex10, regulating tumor cell growth, viability, proliferation, invasion, apoptosis, and stemness, as well as Wnt1/β-catenin signaling." (PMID 41440381, 2025). "Multivariate Cox proportional hazards regression analysis revealed that the TEX10 level, together with the tumor invasion depth, lymph node status, distant metastasis status, stage, and preoperative CA199 level were significantly correlated with both overall survival and progression‐free survival." (PMID 32995120, 2020).
TEX10 also shares sentences with these, for which no sentence is quoted: breast carcinoma (2 papers); Arthritis (1); colon cancer (1); esophageal cancer (1); esophageal SCC (1); gastrointestinal tumors (1); infection (1); infertile (1); prostate carcinoma (1); rheumatoid arthritis (1); teratozoospermia (1).